ITGB4 (integrin subunit beta 4)
Description:
Integrin alpha-6/beta-4 is a receptor for laminin. Plays a critical structural role in the hemidesmosome of epithelial cells. Is required for the regulation of keratinocyte polarity and motility. ITGA6:ITGB4 binds to NRG1 (via EGF domain) and this binding is essential for NRG1-ERBB signaling. ITGA6:ITGB4 binds to IGF1 and this binding is essential for IGF1 signaling. ITGA6:ITGB4 binds to IGF2 and this binding is essential for IGF2 signaling.
Synonyms: CD104; GP150; JEB5A; JEB5B
Tractability: Small molecule: it has a binding pocket of medium quality; it belongs to a druggable protein family. Antibody: its Gene Ontology location is reachable by antibodies, with high confidence; UniProt places it where antibodies can reach, with medium confidence; UniProt predicts a signal peptide or a membrane-spanning region; the Human Protein Atlas places it where antibodies can reach. PROTAC: ubiquitination databases record sites on it.
Gene: Protein-coding gene on chromosome 17 (75,721,190 to 75,757,821, forward strand). Ensembl gene ENSG00000132470.
Subcellular location: Cell membrane; Cell junction, hemidesmosome
Subcellular location (Human Protein Atlas): Cell Junctions; Plasma membrane
Pathways (Reactome):
Extracellular matrix organization: Assembly of collagen fibrils and other multimeric structures; Laminin interactions; Syndecan interactions
Cell-Cell communication: Type I hemidesmosome assembly
Developmental Biology: Differentiation of Keratinocytes in Interfollicular Epidermis in Mammalian Skin
Gene Ontology:
Molecular function: G protein-coupled receptor binding; insulin-like growth factor I binding; neuregulin binding; protein binding; integrin binding
Biological process: autophagy; cell motility; cell-matrix adhesion; hemidesmosome assembly; mesodermal cell differentiation; nail development; response to wounding; skin morphogenesis; cell adhesion; cell adhesion mediated by integrin; cell migration; cell-cell adhesion; integrin-mediated signaling pathway; anatomical structure formation involved in morphogenesis; cell communication
Cellular component: cell junction; cell leading edge; cell surface; extracellular exosome; hemidesmosome; plasma membrane; receptor complex; focal adhesion; integrin complex; membrane
Genetic constraint (gnomAD): Loss-of-function variants: 158 observed, 209.55 expected, observed/expected ratio (o/e) 0.75, 90% interval 0.66 to 0.86. The upper end of that interval is the gene's LOEUF score, 0.86, which puts it in group 3 of 6, group 1 being the genes least tolerant of losing a copy. Missense variants: 2,274 observed, 2,578.4 expected, observed/expected ratio (o/e) 0.88, 90% interval 0.85 to 0.91. Synonymous variants: 1,016 observed, 1,071.5 expected, observed/expected ratio (o/e) 0.95, 90% interval 0.9 to 1.
Homologues: Orthologues: chimpanzee ITGB4 (99% identical), macaque ITGB4 (98% identical), guinea pig ITGB4 (88% identical), mouse Itgb4 (88% identical), pig ITGB4 (88% identical), dog ITGB4 (88% identical), rat Itgb4 (87% identical), rabbit ITGB4 (81% identical), tropical clawed frog itgb4 (59% identical), zebrafish itgb4 (53% identical). Paralogues in human: ITGB3 (16% identical), ITGB5 (16% identical), ITGB1 (16% identical), ITGB6 (15% identical), ITGB7 (15% identical), ITGB2 (14% identical), ITGB8 (12% identical), ITGBL1 (7% identical).
Diseases named in the same sentence as ITGB4 in open-access papers:
ITGB4 is named in the same sentence as 128 diseases in open-access papers, as found by Europe PMC text mining. Sharing a sentence is not in itself a finding about the gene and the disease. The quoted sentences say what the papers report.
breast carcinoma (51 papers, 2014 to 2026). "Caveolin-1 (P132L), a frequently occurring mutation in breast cancer, has been shown to selectively enhance the expression of ITGB4." (PMID 39169946, 2024). "To examine the clinical association of PTPRZ1 with integrin β4 (ITGB4) in breast cancer, we assessed the correlation of ITGB4 and PTPRZ1 by analyzing the data from the TCGA PanCancer Atlas Breast Invasive Carcinoma Dataset." (PMID 39518121, 2024). "ITGB4 has been implicated in promoting the invasive potential of various squamous cell carcinomas, breast cancers, and gastric cancers by activating MAPK and NF-κB signaling pathways." (PMID 39169946, 2024). "For example, patients carrying the A allele for SNP rs743554, located within a predicted miRNA binding site of the integrin beta 4 (ITGB4) gene, were found to be at increased risk for ER- breast cancer (OR=2.09; 95% CI=1.19-3.67)." (PMID 31379942, 2019). "ITGB4 is highly expressed in multiple tumors, such as lung carcinoma, prostate cancer, colorectal cancer and breast cancer, and is implicated in clinical investigation." (PMID 26918348, 2016). "In this study, we provided significant insights into the novel antimetastatic mechanism of the neddylation inhibitor MLN4924, resulting from its ability to promote histone lactylation and suppress ITGB4 expression in breast cancer cells." (PMID 40784455, 2025). "To investigate its role in breast cancer cells, we first knocked down ITGB4 via siRNA silencing and found that capabilities of migration and invasion were significantly inhibited in breast cancer cells." (PMID 40784455, 2025). "Cancer cells residing in a partial EMT state were isolated from the basal-like breast cancer subtype based on CD104 (β4 integrin) (ITGB4) and CD44 cell surface expression." (PMID 40764669, 2025). "Collectively, these results indicated that MLN4924 effectively suppresses breast cancer cell metastasis, at least in part, by epigenetically downregulating ITGB4 expression via inducing H3K18 lactylation." (PMID 40784455, 2025). "Histone H3K18 lactylation within the first intron region of the ITGB4 gene suppresses its expression and ultimately inhibits in vitro migration and invasion and in vivo metastasis of breast cancer cells." (PMID 40784455, 2025). "Biologically, MLN4924 effectively suppresses the migration and invasion of breast cancer cells in vitro and metastasis in vivo, which is largely rescued by ITGB4 overexpression." (PMID 40784455, 2025). "Taken together, our study revealed a new mechanism by which MLN4924 suppresses the migration and invasion of breast cancer cells by epigenetically inhibiting ITGB4 expression via enhancing H3K18 lactylation." (PMID 40784455, 2025). "Our study revealed a novel neddylation-independent mechanism by which MLN4924 suppressed the migration and invasion of breast cancer cells in vitro and metastasis in vivo via epigenetically targeting ITGB4." (PMID 40784455, 2025). "High ITGB4 expression is a prognostic factor in CRC and is associated with drug resistance mechanisms in breast cancer, such as resistance to tamoxifen-induced apoptosis via the PI3K/Akt pathway and anoikis resistance through RAC1 signaling." (PMID 39401197, 2024). "Breast cancer cells can also utilize surface ITGB4 to isolate a highly enriched population of human breast cancer stem cells (CSCs), and the gene regulatory network operating in ITGB4 (+) CSCs has been identified." (PMID 39239559, 2024). "Breast cancer cells-derived exosomes were also evidenced to induce mitophagy and glycolysis in CAFs via delivering integrin beta 4 (ITGB4)." (PMID 38802766, 2024). "The expression of ITGB4 is up-regulated in multiple malignant tumors such as breast cancer, lung cancer and liver cancer, which is related to the dismal patient prognosis." (PMID 38831335, 2024). "SPARC acts as a downstream effector molecule that amplifies ITGB4-mediated invasion in breast cancer." (PMID 39169946, 2024).
breast carcinoma (continued). "Co-culture assays revealed that the level of ITGB4 expression directly correlated with enhanced breast cancer cell proliferation, EMT, and invasion." (PMID 39169946, 2024). "Historically, on the basis of analyses in human cancer tissue samples, ITGB4 is regarded as an unfavorable prognosis marker in breast cancer, lung cancer and colorectal cancer." (PMID 37371594, 2023). "(J–N) ITGB4 depletion promotes HCC1806 breast cancer cell sensitivity to EPI and BMN treatment in vivo." (PMID 37787041, 2023). "It has confirmed that EGFR phosphorylation was regulated by ITGB4 in gastric cancer, breast cancer and liver cancer." (PMID 34975337, 2022). "ITGB4 expression was already described in various malignant tumors including prostate cancer and breast cancer." (PMID 36295095, 2022). "For example, ITGB4 promotes cell invasion in hepatocellular carcinoma and breast cancer metastases, and ITGB4 expression has been identified as a prognostic marker in pancreatic ductal cancer, colon cancer, and head and neck squamous cell carcinomas." (PMID 35250607, 2022). "Recent studies demonstrated that ITGB4 played an important role in promoting tumorigenesis in prostate cancer, breast cancer, gastric cancer, and lung squamous cell carcinoma." (PMID 34545326, 2021). "For example, deletion of the ITGB4 signaling domain in a mouse model of ErbB2-induced mammary carcinoma resulted in suppression of tumor growth and metastasis, and improved efficacy of ErbB2-targeted therapy." (PMID 34504657, 2021). "ITGB4 was found to have a strong positive correlation with tumor size (p = 0.01) and tumor nuclear grade (p < 0.01) in early breast cancer." (PMID 31875161, 2019). "NFATC1 binds to the ITGB3 promoter in osteoclast precursor cells, while NFATC2 and NFAT5 promote ITGA6/ITGB4-mediated cell invasion in breast cancer." (PMID 31730483, 2019). "There is increasing evidence to indicate that the overexpression of ITGB4 is correlated with an aggressive phenotype and poor prognosis in breast cancer, lung cancer, pancreatic cancer, cervical cancer, and gastric cancer." (PMID 30658712, 2019). "al. demonstrated that ITGB4 augments HER2 signaling to promote breast cancer progression, while another study by Wang et." (PMID 24729020, 2014). "ITGB4 is of special prognostic significance in basal type breast cancer exemplified by MDA-MB-231 cells used in this study." (PMID 24729020, 2014). "ITGB4 (Integrin β4) contributes to HER2 up-regulation in mammary tumors suggesting a strong correlation between HER2 and integrins in mammary tumor development and progression." (PMID 24729020, 2014). "Additionally, we demonstrated that MLN4924 significantly suppresses ITGB4 expression and migration and invasion of breast cancer cells, providing new insights into its regulation and potential therapeutic targeting." (PMID 40784455, 2025). "Moreover, MLN4924, while dose-dependently reducing ITGB4 expression, also suppressed the migration and invasion of breast cancer cells in a dose-dependent manner." (PMID 40784455, 2025). "ITGB4 regulates the migration and invasion of breast cancer." (PMID 39169946, 2024). "Interestingly, breast cancer cells with low ITGB4 expression exhibit a concomitant decrease in miR-29a levels." (PMID 39169946, 2024). "ITGB4 is well known to promote breast cancer stemness and can be activated by laminin-5." (PMID 37787041, 2023). "Moreover, Park & al. demonstrated in MCF10 breast cancer cells overexpressing SRSF6 that ITGA5, ITGB2 and ITGB6 were overexpressed and alternative splicing variants of ITGB2, ITGB4, SRSF6 and ATXN2 were detected." (PMID 37904233, 2023). "In addition, the expression of ITGB4 on ALDHhigh breast cancer and head and neck cancer cells was significantly greater than that on ALDHlow cells, proving the effects that ITGB4 targets on both bulk and CSC populations." (PMID 37787041, 2023). "Hence, ITGB4 is recognized as prognostic marker with mechanistic implication in tumor progression of breast cancer." (PMID 36076232, 2022).
breast carcinoma (continued). "Studies have also demonstrated that knockdown of vimentin resulted in downregulation of genes involved in breast cancer invasion and the basal-like phenotype, including Axl, ITGB4, and PLAU, with a subsequent upregulation in the genes abundant in normal mammary epithelium, including RAB25 and EHF." (PMID 34769002, 2021). "Recent studies showed that ITGB4 has an important role in promoting carcinogenesis in prostate cancer, breast cancer, gastric cancer, and lung squamous-cell carcinoma, as well as that ITGB4 is involved in the invasion and metastasis of breast and prostate cancer." (PMID 31242404, 2020). "Mechanistically, PTEN up-regulates MALAT1 expression by binding and sequestering miR-17, miR-20a and miR-106b, and MALAT1 suppresses colorectal and breast cancer cell migration and invasion by reducing the pro-metastatic Epithelial Cell Adhesion Molecule (EpCAM) and ITGB4." (PMID 32174966, 2020). "Notably, CuB inhibited ITGA6 and ITGB4 (integrin α6 & integrin β4), which are overexpressed in breast cancer." (PMID 24729020, 2014). "Finally, public breast cancer database analyses demonstrated that ITGB4 correlates with PTPRZ1 and that high expression of ITGB4, UCHL1, HIF1A, and PTPRZ1 associated with decreased overall survival, distant metastasis free survival, post progression survival, and relapse-free survival." (PMID 39518121, 2024). "ITGB4 could also serve as a prognostic marker for breast cancer." (PMID 34402716, 2021). "Moreover, the ITGB4 protein derived from breast cancer exosomes has been shown to upregulate BNIP3L expression in cancer-associated fibroblasts (CAFs), thereby inducing BNIP3L-dependent mitophagy in CAFs and providing energy metabolites for breast cancer cells." (PMID 39472438, 2024). "While our study discovered a significant correlation of ITGB4 and PTPRZ1 in various cancer types, including TNBC, it is worth mentioning that ITGB4 also significantly correlated with PTPRZ1 in luminal breast cancer subtype." (PMID 39518121, 2024). "We found that ITGB4 expression correlated with PTPRZ1 in tumor samples from patients with both invasive breast carcinoma and basal-like breast cancer." (PMID 39518121, 2024). "ITGB4 also promotes breast cancer cell resistance to tamoxifen-induced apoptosis by activating the PI3K/AKT signaling pathway and promotes breast cancer cell resistance to anoikis by activating RAC1." (PMID 37787041, 2023). "Targeting ITGB4 in mouse models of breast cancer and HNSCC with dendritic cells pulsed with ITGB4 protein or with a CD3/ITGB4 bispecific antibody inhibited tumor growth and metastasis formation." (PMID 36076232, 2022). "Both ITGB4 and VCAN are considered to correlate with ECM and promote tumor invasion and metastasis of breast cancer with elevated expression." (PMID 35966872, 2022). "Overexpression of ITGA6 and ITGB4 attenuated the ferroptosis induced by erastin, while knockout of ITGA6 and ITGB4 promoted ferroptosis in breast cancer cells." (PMID 34277151, 2021). "In both the 4T1 mouse metastatic mammary tumor model and SCC7 head and neck squamous cell carcinoma model, integrin β4 (ITGB4) was expressed on ALDHhigh 4T1 and SCC7 CSCs." (PMID 34504657, 2021). "By forming a RNA-protein complex with TEAD and down-regulating EpCAM, ITGB4 and VEGF expression, MALAT1 suppresses colorectal and breast cancer cell migration, invasion, and metastasis." (PMID 32174966, 2020). "In breast cancer, ZEB1 represses the expression of the epithelial transcription factor TAp63α (tumor protein 63 isoform 1) and promotes ITGB4 (also known as CD104) expression, which allows the cells to present as tumor-initiating cells." (PMID 32143517, 2020). "Notably, similar to human breast cancer cells, 4T1 cells also responded to MLN4924 treatment with increased H3K18 lactylation and reduced ITGB4 expression." (PMID 40784455, 2025).
breast carcinoma (continued). "Gene expression analysis showed that GPNMB+ cells significantly upregulated genes involved in invasion and/or tissue remodeling, including EGFR, a direct interactor of GPNMB in breast cancer cells, its downstream targets (STAT3, MMP 2-3-9) and ITGB4, TGFβ, VEGF and VCAM." (PMID 40528051, 2025). "Paricalcitol inhibits the expression of ITGA6, ITGB4, and α-SMA in human breast cancer cells." (PMID 40386428, 2025). "ITGB4-overexpressing triple negative breast cancer cells provided CAFs with ITGB4 proteins via exosomes, which induced BNIP3L-dependent mitophagy and lactate production, and then promoted the proliferation, EMT and invasion of breast cancer cells." (PMID 38825680, 2024). "Since PTN and PTPRZ1 are both expressed in different subtypes of breast cancer and PTN is also found in normal breast tissues, it will be interesting to investigate how the correlation of ITGB4 and PTPRZ1 contributes to luminal cancer progression and therapeutic response." (PMID 39518121, 2024). "Through the acquisition of adhesion ability, the integrins ITGB2, ITGB4, and ITGA10 may promote the attachment of breast cancer cells to the extracellular matrix and thereby enhance metastasis." (PMID 36910659, 2023). "Supporting this hypothesis, depletion of ITGB3, ITGB4 and ITGB5 reduced angiogenesis and tumor growth in breast cancer." (PMID 37215577, 2023). "In summary, ITGB4 and TNFAIP2 play important roles in breast cancer chemoresistance." (PMID 37787041, 2023). "Moreover, ITGB4 transactivates EGFR/Her2 signaling and promotes lung metastasis in breast cancer cells." (PMID 34693476, 2022). "EMT states were first stratified by CD44 and CD24, and later by CD104 (ITGB4), to identify tumorigenic populations of cells, linking the invasive and disease progressing nature of EMT to stem-like processes of cancer stem cells, particularly in breast cancer." (PMID 35267444, 2022). "Differentially expressed genes, especially those in five modules, including OAS1, IFI27, LPAR1, PTGFR, ITGB4, and ITGA6, might participate in the epithelial-mesenchymal transition process in breast cancer cell line DKTA." (PMID 36289533, 2022). "The observed loss of SAFB1 in both breast cancer cell lines does not have an effect on ITGB4 mRNA expression whereas loss of SAFB2 and both SAFB proteins significantly increased ITGB4 expression." (PMID 26273616, 2015). "Interestingly, ITGB4 also significantly correlated with PTPRZ1 in breast cancer Luminal A subtype, but not Luminal B or Her2 breast cancer subtypes." (PMID 39518121, 2024). "Furthermore, ITGB4-overexpressing TNBC cells provided cancer-associated fibroblasts (CAFs) with ITGB4 proteins via exosomes, and ITGB4-overexpressing CAF-conditioned medium promoted the proliferation, epithelial-to-mesenchymal transition, and invasion of breast cancer cells." (PMID 37787041, 2023). "Interestingly, blocking the SRC/EGFR-dependent ITGB4/FAK pathway, which subsequently inactivates the Akt and p38/MAPK pathways contributes to the suppression of migration and invasiveness of breast cancer cells and reversal of EMT process after treatment with Ziyu II." (PMID 35379785, 2022). "We examined its selectivity for inducing apoptosis in cells with differential expression of ITGB4: hepatic cells (L-02), human embryonic kidney cells (HEK293), and 4 kinds of tumor cells – prostatic cancer (PC3), lung carcinoma (A549), colorectal cancer (HCT116) and breast cancer (MCF-7)." (PMID 26918348, 2016).